NQO1 (NAD(P)H quinone dehydrogenase 1)
Diseases named in the same sentence as NQO1 in open-access papers (continued):
Sharing a sentence is not in itself a finding about the gene and the disease.
Hyperglycemia (22 papers, 2016 to 2025). An increased concentration of glucose in the blood. "Our study demonstrates the compartment-specific impact of NQO1 deficiency under STZ-induced hyperglycemia, providing new insight into its functional roles in diabetic kidneys." (PMID 40920692, 2025). "Together, these results suggest that NQO1 deficiency exacerbates hyperglycemia-induced glomerular injury, as reflected by worsened albuminuria and structural abnormalities." (PMID 40920692, 2025). "In the present study, we found that the NQO1 overexpression reversed the decrease in intracellular NAD+ levels caused by hyperglycemia." (PMID 35090502, 2022). "In this regard, part of NQO1’s protective role in hyperglycemia is clearly ROS-dependent, particularly in preventing ROS-induced damage to glomerular and tubular cells." (PMID 40920692, 2025). "Streptozotocin (STZ)-induced hyperglycemia increased albuminuria and foot process effacement, with NQO1 KO (NKO) mice exhibiting greater podocyte injury than WT, indicating exacerbated glomerular damage." (PMID 40920692, 2025). "Our in vitro and in vivo studies revealed that hyperglycemia significantly increased Keap1 expression and inhibited Nrf2 and NQO1 expression, whereas PET treatment reversed these trends and improved oxidative stress and ferroptosis." (PMID 41181708, 2025). "Treatment of hyperglycemic zebrafish with vitamin D and SFN has reduced the hyperglycemia-induced NQO1 activity." (PMID 36358486, 2022). "In the current study we shown that under hyperglycemia condition antioxidants like NQO1, SOD1 were upregulated and Gpx1 was down regulated and upon vitamin-D treatment this conditioned were normalized." (PMID 36358486, 2022). "Upregulation of Nqo1 in cultured vascular cells by adenovirus vectors also decreased the expression of hyperglycemia-mediated endothelial adhesion molecule and tumor necrosis factor -α and prevented smooth muscle cell migration." (PMID 35739970, 2022). "Overexpression of NQO1 can partly restore Nrf2 suppression-mediated oxidative stress in hyperglycemia or diabetic conditions, but cannot completely restore this effect." (PMID 31616304, 2019). "We evaluated the potential effect of hyperglycemia on the expression of Nrf2 and its target genes NQO1 and HO1." (PMID 31616304, 2019). "It is known that hyperglycemia results in significant reduction of the Nrf2 expression and its downstream proteins (HO-1, NQO-1)." (PMID 31583254, 2019). "Further investigation showed that either Nrf2 overexpression or Nrf2 activator DMF treatment restores hyperglycemia-induced oxidative stress with up-regulated NQO1 and HO1 as well as decreased secretion of inflammatory cytokines." (PMID 31616304, 2019). "While hyperglycemia reduced the expression of Nrf2, HO-1, and NQO-1, PHL markedly upregulated these genes in vitro and in vivo." (PMID 30619098, 2018). "In our in vitro and in vivo models of hyperglycemia, PPARβ/δ activation significantly reduced Nrf2 and NQO-1 expression, whereas upregulating HO-1." (PMID 30046379, 2018). "This increase in Nrf2 expression and/or Nrf2's downstream antioxidant genes (NQO1 and HO-1) in response to hyperglycemia was evident in diabetic mouse hearts." (PMID 29721501, 2018). "In our in vitro hyperglycemia model, HUVECs exhibited upregulated gene and protein expression of Nrf2 along with increased expression of NQO-1 and HO-1, adding support to the previous findings." (PMID 30046379, 2018). "CoPP treatment inhibited allodynia, hyperglycemia and body weight gain in db/db mice by enhancing HO-1/NQO1 levels and reducing JNK phosphorylation." (PMID 29143802, 2017). "NQO1 is other enzyme also involucrate in the protection against oxidative stress, as demonstrated by the increased reactive oxygen species and hyperglycemia produced by the disruption of this gene in mice." (PMID 29143802, 2017).
Hyperglycemia (continued). "Based on the distinct structural and metabolic characteristics of the glomerulus and proximal tubule, we hypothesized that NQO1 plays a protective role against hyperglycemia-induced oxidative stress in a compartment-specific manner." (PMID 40920692, 2025). "As a downstream effector of the Nrf2 pathway—currently being targeted in clinical trials with agents such as bardoxolone methyl—NQO1’s modulation may offer compartment-specific protection against hyperglycemia-induced injury." (PMID 40920692, 2025). "It was discovered through this study that hyperglycemia could inhibit the Nrf2 signaling pathway to decrease the downstream HO-1 and NQO-1, and GF was able to further repress the Nrf2 signaling pathway to exacerbate oxidative injury in the hippocampus." (PMID 38282656, 2024). "It has been found that antrodin C has anti-inflammatory effects in RAW264.7 macrophages activated by LPS and can effectively interfere with hyperglycemia-induced senescence and apoptosis by activating the HO-1/NQO-1-dependent cellular antioxidant defense system." (PMID 34638752, 2021). "Furthermore, both STZ and hyperglycemia have been known to increase ROS production, and NQO-1 enzyme plays an important role as a superoxide scavenger that may provide an additional level of protection against ROS toxicity." (PMID 26839634, 2016). "Addition of vitamin D and SFN increased Nrf2, but differentially modulated its target genes (NQO1, SOD, GPx etc) activity in zebrafish and neuronal cell lines thereby improved the hyperglycemia-induced decline of cognition impairment." (PMID 36358486, 2022). "However, ROS generation and gene expression of anti-oxidant enzymes in whole kidneys in response to STZ-induced hyperglycemia was not affected by NQO1 deficiency, suggesting that oxidative stress is not a major contributor to the development of renal injury in NKO mice with DN." (PMID 33082368, 2020). "The gene expression showed that Nrf2, NQO-1, and HO-1 were significantly increased in the PHL pre-treated group despite hyperglycemia induction." (PMID 30619098, 2018). "Transcript levels of Nqo1 and Sod2 were significantly elevated in STZ-diabetic mice following acute hypoglycaemia (STZ-LH vs WT-EE; p<0.05 for both genes), and the levels of Sod2 were further increased (>fivefold) in chronic hyperglycaemia." (PMID 37015997, 2023). "Hyperglycemia is known to modulate the antioxidant defense enzymes GPX, SOD and NQO1." (PMID 36358486, 2022). "Here, we show that hyperglycemia-induced oxidative stress and ER stress increased the expression of p-PERK in STZ-induced DPN rats, promoted the dissociation of Nrf2 from Keap1 to induce the expression of HO-1, γGCS, GST and NQO1." (PMID 28432299, 2017). "DHA, in particular, may elicit an effective antioxidant response against hyperglycemia-induced oxidative stress and apoptotic pathways by promoting the formation of the reductive agent NADH in the cytoplasm and, therefore, maintaining the activation of the Nrf2/Nqo1 signaling cascade." (PMID 35739970, 2022).
Alzheimer disease (21 papers, 2013 to 2025). A progressive, neurodegenerative disease characterized by loss of function and death of nerve cells in several areas of the brain leading to loss of cognitive function such as memory and language. "Researchers have found that NQO1 is associated with aging and early pathological changes in Alzheimer’s disease (AD)." (PMID 37182175, 2023). "NQO-1 and HO-1 are both enzymatic regulators of antioxidant capacity and have been found to be associated with different diseases, including cancer and Alzheimer’s disease." (PMID 33383921, 2020). "Chhetri and colleagues recently reported an association between Alzheimer’s disease-related cognitive decline and the downregulation of the Nrf2 system, which also involves NQO1." (PMID 30934852, 2019). "The abnormalities of NQO1 enzyme activity have been linked to the pathophysiological mechanisms of multiple neurological disorders, including Parkinson's disease, Alzheimer's disease, epilepsy, multiple sclerosis, cerebrovascular disease, traumatic brain injury, and brain malignancy." (PMID 38167027, 2024). "In addition, due to its essential role in redox processes, NQO1 was associated with other diseases, such as multiple sclerosis, Alzheimer’s disease, type 2 diabetes, and metabolic syndrome." (PMID 37583897, 2023). "Alterations in NQO1 stability and function are associated to different extents with a variety of human diseases, including cancer, neurological disorders (such as Parkinson ́s and Alzheimer ́s diseases, multiple sclerosis and schizophrenia) and cardiovascular diseases." (PMID 31726777, 2019). "Our search identified NQO1 as elevated (p < 0.01) in patients with neurological diseases, including Parkinson disease and Alzheimer disease." (PMID 41109135, 2025). "While modulation of the HO-1 system plays an important role in the development of Alzheimer’s disease, activation of the NQO1 protein is critical for reducing apoptosis in PC12 cells." (PMID 39457556, 2024). "NQO1 (NAD(P)H quinone dehydrogenase 1) has multiple functions and has been linked to Alzheimer’s disease." (PMID 38295113, 2024). "It is relevant to note that NQO1 levels are increased in patients of diseases that involve high levels of oxidative stress, such as Alzheimer’s disease." (PMID 37508002, 2023). "For instance, a previous study demonstrated that dual BACE-1/GSK-3β inhibitors act through the inhibition of the NQO1 enzyme in order to counteract the oxidative stress in Alzheimer's disease." (PMID 33087132, 2020). "Human NAD(P)H:quinone oxidoreductase 1 (NQO1) is a multi-functional protein whose alteration is associated with cancer, Parkinson’s and Alzheimer ́s diseases." (PMID 31726777, 2019). "NAD(P)H Quinone Dehydrogenase 1 is a detoxifying enzyme that is elevated in the brain in neurotoxic conditions and early stage Alzheimer’s disease." (PMID 28659758, 2017). "Although increased NQO1 is evident in hippocampal and frontal cortex neurons in Alzheimer’s disease brain, NQO1 is strongly increased in astrocytes near plaques in both regions." (PMID 28820437, 2017). "But then Nrf2 and NQO1 expression quickly decline with age, with similar NQO1 expression as controls from 4–6 months of age and lower Nrf2 expression in Alzheimer’s disease mice from 11–21 months of age." (PMID 28820437, 2017). "Other reports indicate that altered NQO1 expression is related to the pathogenesis of Alzheimer°s disease (AD), and suggest a potential neuroprotective role for NQO1 in diseases involving metabolic and oxidative stresses including AD." (PMID 23874855, 2013). "In the brain, HO-1 has been shown to be cytoprotective in models of stroke, excitotoxicity, Parkinson’s disease, and Alzheimer’s disease while NQO1 has been shown to be protective against a model of Parkinson’s disease." (PMID 23922950, 2013).
liver cancer (19 papers, 2019 to 2025). An epithelial or non-epithelial malignant neoplasm that arises from the liver. "In NQO1-defective liver cancer cells, both glycolysis and glutaminolysis-associated gene expressions are suppressed by AKT." (PMID 35624775, 2022). "NQO1 potentiates the apoptosis evasion of liver cancer cell through upregulating X-linked inhibitor of apoptosis protein (XIAP) protein stability." (PMID 31842909, 2019). "The risk model for liver cancer patients includes NQO1, NT5DC2, and S100A9 as risk genes." (PMID 37405532, 2024). "The positive rates for NRF2 and NQO1 were significantly higher in liver cancer tissues than in normal liver tissues." (PMID 40007539, 2025). "In this study, we find that DPP9 weakens the responses of liver cancer cells to chemotherapy drugs by up-regulating NQO1 and inhibiting intracellular ROS levels." (PMID 39094401, 2024). "Collectively, our findings suggest that inhibiting DPP9/NQO1 signaling can serve as a potential therapeutic strategy for liver cancer." (PMID 39094401, 2024). "Next, we evaluated the effect of dicoumarol (an NQO1 inhibitor) on the efficacy of chemotherapy drugs in liver cancer cells." (PMID 39094401, 2024). "Several studies have confirmed that NQO1 mRNA levels in liver cancer tissues are significantly upregulated compared with that in non-liver cancer tissues." (PMID 37405532, 2024). "In this study, we find that DPP9 can inhibit ROS levels in liver cancer cells by up-regulating NQO1." (PMID 39094401, 2024). "DPP9 and NQO1 protein levels in liver cancer and adjacent normal tissues were detected by using immunohistochemical (IHC) assay." (PMID 39094401, 2024). "Since DPP9 can regulate NQO1 in liver cancer cells, does DPP9 affect chemoresistance in liver cancer cells by regulating NQO1?" (PMID 39094401, 2024). "It has been reported to possess anti-liver cancer activity by inhibiting the NAD(P)H:quinone oxidoreductase 1 (NQO1) enzyme, which is involved in tumor growth and survival pathways." (PMID 37601910, 2023). "The predictive model based on arterial phase CT imaging features has good stability and diagnostic efficiency and is a potential means to noninvasively identify the expression levels of NQO1 in liver cancer tissues." (PMID 37695786, 2023). "In contrast, NQO1 overexpression induces PI3K/AKT activation to improve liver cancer cell proliferation." (PMID 35624775, 2022). "A violin plot shows that the expression of AKR1C3, NQO1, TEK and TPX2 was significantly associated with different disease states (normal, cirrhosis or liver cancer) (p < .05) (GSE54238)." (PMID 36686655, 2022). "Upregulation of NQO1 was frequently observed in various types of cancer, such as breast, prostate, lung and liver cancer." (PMID 33648552, 2021). "It was observed that in breast and liver cancer cell lines, lycopene promoted the upregulation of genes for NAD(P)H:quinone oxidoreductase 1 (NQO1), glutamate cysteine ligase (GCL) and glutathione (GSH), by activating Nrf2." (PMID 34948455, 2021). "Together, these results indicate that the NQO1:CAT ratio is an ideal therapeutic window in liver cancer for NQO1 bioactivatable drugs." (PMID 34676172, 2021). "Our previous study has demonstrated that NAD(P)H: quinone oxidoreductase 1 (NQO1) is significantly upregulated in human liver cancer where it potentiates the apoptosis evasion of liver cancer cell." (PMID 31842909, 2019). "Since the ratio of intracellular NAD(P)H/NAD(P)+ plays an important role in regulating ROS levels to maintain redox homeostasis, up-regulation of NQO1 may inhibit ROS levels by influencing the ratio in liver cancer cells." (PMID 39094401, 2024). "In addition, the NQO1 inhibitor dicoumarol can enhance the efficacy of chemotherapy drugs in liver cancer cells." (PMID 39094401, 2024).
liver cancer (continued). "This study reveals that DPP9 inhibits ubiquitin-mediated degradation of NRF2 protein by binding to KEAP1, up-regulates NRF2 protein levels, promotes mRNA transcription of NQO1, inhibits intracellular ROS levels, and thus weakens the responses of liver cancer to chemotherapy drugs." (PMID 39094401, 2024). "In liver cancer, it has been reported that NQO1 was increased 18-fold in HCC versus normal livers." (PMID 34676172, 2021). "To investigate whether the NQO1:CAT ratios are a potential therapeutic window in liver cancer, we analyzed NQO1 and CAT expression in liver hepatocellular carcinoma (LIHC) from The Cancer Genome Atlas (TCGA)." (PMID 34676172, 2021). "Interestingly, we found that DPP9 could regulate ROS levels in liver cancer cells, and this regulatory effect was dependent on NQO1." (PMID 39094401, 2024). "Furthermore, the data presented in this study reveal that NQO1 and the NQO1:CAT ratio could be used as biomarkers to examine the efficacy of NQO1 bioactivatable drugs in HCC or other kinds of liver cancers." (PMID 34676172, 2021). "Functional experiments have revealed that NQO1 not only activates the transcriptional activity of SREBP1 to promote the progression and metastasis of liver cancer but also promotes the growth and invasion of liver cancer via the ERK/p38-NRF2 signaling pathway." (PMID 37405532, 2024). "We thus analyzed the basal NRF2 protein level and the expression of NQO1, an NRF2 target gene, in a panel of five liver cancer cell lines, namely Sk-hep1, HepG2, Hep3B, PLC/PRF/5, Huh7, and Mahlavu." (PMID 33915987, 2021). "Recently, NQO1 overexpression was reported to be a potent independent biomarker for prognostic evaluation of HCC and enhanced apoptosis inhibition of liver cancer cells via the SIRT6/AKT/XIAP signaling pathway." (PMID 34676172, 2021). "Since we have shown that DPP9 can regulate the mRNA levels of NQO1 in liver cancer cells, the question arises as to whether DPP9 also has an impact on the protein stability of NQO1." (PMID 39094401, 2024). "There was no discernible difference in the rate of NQO1 protein degradation in SK-Hep-1 and HepG2 cells following the overexpression and silencing of DPP9, indicating that DPP9 does not affect the levels of NQO1 protein in liver cancer cells by regulating the stability of NQO1 protein." (PMID 39094401, 2024). "On the other hand, similar to the analysis in HCC patient samples, we observed that the liver cancer cell lines HepG2, Huh7 and Li7 showed high NQO1 levels; PLC/PRF/5 cells exhibited moderate NQO1 expression; and Hep3B, SNU-182, and SK-HEP1 cells expressed low or undetectable NQO1." (PMID 34676172, 2021). "However, it is not clear how up-regulated NQO1 regulates ROS levels in liver cancer cells." (PMID 39094401, 2024). "However, RNA sequencing result shows that apart from NQO1 gene, there is no significant up-regulation observed for other NRF2 downstream target genes in liver cancer cells with DPP9 overexpression." (PMID 39094401, 2024).